BCL2 (BCL2 apoptosis regulator)
Diseases named in the same sentence as BCL2 in open-access papers (continued):
Sharing a sentence is not in itself a finding about the gene and the disease.
tumor (continued). "Alternatively, BCL2 down-regulation could be an unsuccessful attempt of the tumor cells' genetic program to shift the cellular homeostasis towards cell death." (PMID 16982006, 2006). "Bcl-2-positive cells in mammary glands and cellular apoptosis in tumour tissue were also studied." (PMID 15987453, 2005). "Overexpression of Bcl-2 protein was detected in the cytoplasm of 199/437 evaluable tumours (45.5%)." (PMID 16029489, 2005). "The overexpression of bcl-2 and bcl-XL proteins by the tumour cells may create a block to radiotherapy-induced apoptosis." (PMID 15928664, 2005). "However, the relevance of apoptotic modulation by Bcl-2 and related proteins in tumour development and radiation response for human tumours remains undefined." (PMID 15685241, 2005). "Resistance to apoptosis has important implications for the efficacy of chemotherapy and radiotherapy because tumor cells that overexpress either bcl-2 or bcl-xL may be resistant to either mode of cancer therapy." (PMID 16185362, 2005). "In addition, many genes in the combined list are prominent oncogenes or tumour suppressors, like BCL2 or ERBB3." (PMID 16271137, 2005). "Bcl-2 and bcl-XL staining was localised to the tumour cell cytoplasm." (PMID 15928664, 2005). "Although no strong associations between Bcl-2 expression and clinico-pathological variables were noted, there was a trend on univariate analysis towards increased cytoplasmic accumulation of Bcl-2 in moderate and poorly differentiated tumours compared with well differentiated tumours (p = 0.076)." (PMID 16029489, 2005). "Bcl2 expression with 100% of the tumor cells positive was observed in 4 of 11 (36%) cases." (PMID 15357873, 2004). "Since the mithramycin/TNF combination is capable of inducing apoptosis in TF-1 cells independently of the mitochondrial pathway, combining TNF treatment with mithramycin could have potential for elimination of tumour cells that express large amounts of Bcl-2." (PMID 15138489, 2004). "BCL2 e proteína nuclear de proliferação celular raramente estão expressados, não havendo correlação destes com as variáveis de prognóstico patológicos nessa neoplasia." (PMID 15448811, 2004). "On the other hand, Bcl-2 as an antiapoptotic molecule protects tumour cells from induced apoptosis and may render RCC resistant to all kinds of apoptotic–triggering therapeutics, including chemotherapy and irradiation." (PMID 14710230, 2004). "Moreover, the cutoff in the number of positive cells defining a tumour with Bcl-2 overexpression is often arbitrary and varies according to the investigators, from a few percent to 50%." (PMID 12838300, 2003). "Similarly, a significant difference in the expression patterns of Bcl-XL and Bcl-2 was observed by immunostaining of the tumour samples using anti-Bcl-XL and anti-Bcl-2 antibodies." (PMID 12644829, 2003). "However, it should be highlighted that tumour Fas and FasL, and Bcl-2 and Bax systems were similar in the two tumour types." (PMID 12610520, 2003). "On the other hand, considering how rarely extrathoracic metastasis in NSCLC express Bcl-2, it could be proposed that this oncoprotein plays an inhibitory role in the haematogenous metastatic process through tumour progression." (PMID 12838300, 2003). "Tumour cells generally have Bcl-2 already induced, thus increasing their resistance to damage." (PMID 14612913, 2003). "Bcl-2 staining of tumour cells was observed in 25 patients (18%)." (PMID 12454767, 2002).
tumor (continued). "They found bcl-2 positivity in a high percentage of initial (91%) and recurrent tumours (97%)." (PMID 12085183, 2002). "In addition, we provide immunostaining data which suggest that bcl-2 protein expression in tumour cells is a useful biological marker for predicting tumour response to induction therapy." (PMID 12454767, 2002). "Bcl-2 acts to extend cell survival by blocking apoptosis, and thereby may influence tumour prognosis." (PMID 12085183, 2002). "Several studies have associated the disorganization of microtubule structure by drugs with mitotic arresting- and apoptosis-inducing activities such as taxol, taxotere, vinblastine, vincristine or the dolastatins with Bcl-2 phosphorylation in various human tumour cell lines." (PMID 11857026, 2002). "Therefore, it seems paradoxical that tumours expressing bcl-2 protein demonstrate an improved therapeutic response." (PMID 12454767, 2002). "These alterations in Bcl-2 expression were reflected by the levels of tumour cell apoptosis." (PMID 11461089, 2001). "Therefore, in addition to its role in angiogenesis and vessel permeability, VEGF acts as a survival factor for tumour cells, inducing Bcl-2 expression and inhibiting tumour cell apoptosis." (PMID 11461089, 2001). "The degree of bcl-2 expression was significantly related with tumour size (P = 0.0155)." (PMID 10646898, 2000). "High proliferation rate and high tumour grade (Bloom-Richardson) were strongly associated with absence of Bcl-2 expression (P< 0.001)." (PMID 9514059, 1998). "Bcl-2 expression was correlated with survival with significantly reduced survival in weakly (P = 0.02) and unstained (P < 0.001) groups compared with those patients having strongly stained malignant tumour cells." (PMID 7577491, 1995). "However, a strong positive relationship was seen between bcl-2 and oestrogen receptor (ER), with 70 of 88 (80%) bcl-2-positive tumours being ER positive also, compared with seven of 23 (30%) bcl-2-negative tumours being ER positive (P < 0.0001)." (PMID 8286195, 1994). "SFXN1 appears to be functionally linked with cell survival and growth promotion genes (AKT1, BCL2, MTOR) and pro-apoptotic components (BAX, CASP3), indicating its dual role in maintaining mitochondrial homeostasis and regulating cell fate decisions in tumor cells." (PMID 41399448, 2026). "Moreover, the intra-T/peri-T Bcl-2+ cell ratio was significantly lower in the CD68+ than CD20+ cell compartment (0.6 ± 0.2 vs 1.3 ± 0.3, p = 1e-13) and Bcl-2+ cell count was lower in the macrophage than tumor cell compartment (292.9 ± 40.7 vs 228.7 ± 26.5, p = 4e-07)." (PMID 41415285, 2025). "In conclusion, based on the results of qPCR, immunohistochemistry, and histopathological analysis, it was found that oral probiotics CB‐AKK could activate the Bcl‐2/Bax pathway to effectively inhibit the proliferation of 4T1 tumor cells and promote the apoptosis of tumor cells." (PMID 40497373, 2025). "Thus, despite in vitro findings of Nef-induced BCL2 upregulation, in vivo HAL tumors may preferentially activate alternative survival pathways such as LMP1-driven NF-κB/PI3K/AKT signaling and MYC amplification, reducing dependency on BCL2 for tumor survival." (PMID 40496610, 2025).
tumor (continued). "This correlation may be due to elevated levels of Bcl-2 protein inhibiting the oligomerization of Bax and Bak within cells, thereby blocking the intrinsic apoptosis pathway, making tumor cells more likely to evade immune surveillance and clearance, and promoting tumor progression and metastasis." (PMID 40497999, 2025). "Indeed, due to venetoclax’s specific targeting of Bcl-2, tumor cells may shift their dependency to other anti-apoptotic proteins such as Bcl-XL, MCL-1 and Bfl-1 for survival." (PMID 40400713, 2025). "In addition, our strategy allowed us to classify the tumor as DLBCL/HGBL-MYC/BCL2 entity." (PMID 39905397, 2025). "This, in contrast to the questionable BCL2 specificity of venetoclax, argues in favor of this protein as a potential predictive biomarker, as immunohistochemical staining is simple, i.e., either scoring as negative or positive (membranous/cytoplasmic staining in ≥30 % of tumor cells)." (PMID 39970625, 2025). "Specifically, the enhanced expression of BCL2 in the context of high Pb levels could indicate a shift towards anti-apoptotic signaling, which not only supports tumor survival but also confers possible resistance to therapies that rely on inducing apoptosis in cancer cells." (PMID 40817076, 2025). "Moreover, Myr-NE tumor samples showed a significant increase in Bax/Bcl2 ratio by 2.86 ± 0.58 fold, which confined to 1.34 ± 0.101 fold in Myricetin tumor, compared with control further confirming the enhanced activation of pro-apoptotic proteins in Myr-NE tumor cells." (PMID 40552278, 2025). "PBX3 could also promote the expression of Bcl-2, leading to the decrease in tumor cell apoptosis." (PMID 40508020, 2025). "Tumor Inhibition: The expression of pro-apoptosis genes Bax, Cyt-C, Apaf-1, caspase-9, and caspase-3 was increased when comparing the Western blotting results to the negative control group, while the expression of anti-apoptosis genes Bcl-2 and Livin was decreased." (PMID 40297577, 2025). "Additionally, it was found that the live bacteria and their metabolites derived from CB‐AKK could inhibit cell proliferation and promote tumor apoptosis by activating the Bcl‐2/Bax signaling pathway." (PMID 40497373, 2025). "Thus, the mechanism by which 6-HMDN induces apoptosis likely involves the Bax/Bcl-2 pathway, which may play a critical role in the anti-tumor activity of 6-HMDN." (PMID 40563454, 2025). "Moreover, the expression levels of CD86 (M1 macrophage marker) and CSF1R (M2 macrophage marker) were positively correlated with those of BECN1 (autophagy regulator) and BCL2 (only CD86) that were in turn correlated with MTOR expression in tumor B cells and in the CD86+ macrophage subtype." (PMID 41415285, 2025). "Additionally, FLT3 inhibitors may modulate BCL-XL and MCL-1 expression, increasing the dependence of tumor cells on BCL-2 and potentially enhancing the efficacy of venetoclax." (PMID 40016600, 2025).
tumor (continued). "This may indicate combination therapy enhances cell’s capacity to react to an apoptotic signal confirmed by the intracellular Bax/Bcl-2 ratio that acts as prognostic indicator for tumor aggressiveness, progression and assesses a cell’s propensity for apoptosis." (PMID 40341222, 2025). "Moreover, for rG4 in the 5′-UTR of Bcl-2, a known anti-tumor target and apoptosis inhibitor, CRISPR-Cas9-based deletion of the rG4-forming sequence from melanoma cell genome caused no changes in mRNA levels, protein levels, or response to apoptosis-activating compounds compared to unedited cells." (PMID 39940956, 2025). "Therefore, the regulation of BCL-2 gene expression is the focus of anti-tumor research." (PMID 38930984, 2024). "Consistent with this hypothesis, we found that multiple BCL2 proteins are transcribed in the primary tumor and early, midpoint, and late metastases, with MCL1 being significantly more abundant compared to other anti-apoptotic factors regardless of the time point." (PMID 37676378, 2024). "Moreover, the immunohistochemical detection of the apoptosis regulators, Bcl2, Bax (also known as Bcl-2-like protein 4), and caspase-3 was performed on tumor slices using biotinylated antibodies, demonstrating the capability of these micelles in inhibiting xenograft tumors." (PMID 39125610, 2024). "We selected two additional tumor models, T11‐UV and T11‐Apobec, that displayed a high expression of Tgfb1 (both tumor models) and Tgfb2 (T11‐UV), high expression of Vimentin (Vim) and fibrotic marker (Pik3ca), and low expression of Cd36 and apoptosis regulator Bcl2." (PMID 39553439, 2024). "In addition, a comprehensive review of iridoids previously reported has shown that many of these molecules are capable of inhibiting tumor cell development, by altering the expression of Bax/Bcl-2, arresting cells in the cell cycle in the G2/M phase, thus preventing their migration and invasion." (PMID 40486278, 2024). "Furthermore, we showed that this effect may be associated with the ability of O. basilicum extract to induce Bcl-2-dependent apoptosis in tumor cells." (PMID 39082586, 2024). "Bcl‐2 was previously shown to be overexpressed in ∼85% of ER+ breast malignancies, and Bcl‐2 positivity has been associated with poor clinical outcome in TNBC models, suggesting possible therapeutic vulnerabilities within both luminal and basal subtyped tumours." (PMID 39417215, 2024). "Tumor cells may also limit apoptosis by molecular processes, such as downregulating proapoptotic genes like Bax and overexpressing antiapoptotic genes like Bcl-2." (PMID 39598770, 2024). "Moreover, Bcl-2 is a tumor suppressor able to inhibit apoptosis and promote cell survival." (PMID 39769425, 2024). "Furthermore, GAs could regulate Bax and Bcl-2 expression, inhibiting Bcl-2 and activating Bax, to trigger tumor cell apoptosis via mitochondrial channel opening and cytochrome C release." (PMID 38519991, 2024). "On the other hand, nicotine can promote the synthesis of anti-apoptotic protein Bcl-2 and inhibit the production of apoptotic protein, thus promoting DNA synthesis and cell proliferation, reducing DNA damage induced by cisplatin and increasing drug resistance of tumor cells." (PMID 38425343, 2024). "In addition, we investigated these tumor sections to detect changes in Bcl-2 conformation." (PMID 38329389, 2024).
tumor (continued). "Meanwhile, rescue experiments with Bcl2‐ and HMG20A‐expressing lentiviral particles were conducted to determine whether the decrease in tumor progression caused by TIPRL depletion was directly linked to the expression of Bcl2 and HMG20A in TIPRL‐depleted cells." (PMID 39076120, 2024). "Therefore, the author utilized folate-modified liposomes (F-PLP) to deliver a plasmid containing BIM-S (a cell death mediator that interacts with BCL-2) to target lung cancer cells and FRβ-positive macrophages in the tumor microenvironment for the significant suppression of in vivo tumor growth." (PMID 39310113, 2024). "In addition, we performed analysis of data from various tumor tissues in the TCGA database to analyze the BCL-2 expression level in patients who received immunotherapy and observed that responders to anti-PD-1 treatment had BCL-2 expression levels comparable to those in nonresponders." (PMID 38062129, 2024). "However, overexpression of BCL2, combined with the cellenONE F1.4 fluorescence imaging application, could serve to identify tumor cells in cases of MRD for further downstream analyses." (PMID 38280422, 2024). "Previous studies have shown that adaptation of tumor cells to VEN is characterized by different mechanisms resulting in functional loss of pro-apoptotic regulators like BAD, BAX, NOXA and PUMA or by a shift in dependency from BCL-2 to other anti-apoptotic proteins like MCL-1." (PMID 38961053, 2024). "Notably, WCP could inhibit the proliferation of H22 tumors not only by improving immune function, but also by promoting the apoptosis of tumor cells, likely through the IL-10/STAT3/Bcl2 and Cyto-c/Caspase8/3 signaling pathways, in H22 tumor-bearing mice." (PMID 37110586, 2023). "The enrichment of ARID1A and KMT2D mutations in BCL2 + FL, independent of the clinical stage, might indicate an altered accessibility to the chromatin structure of the tumor cells." (PMID 37563306, 2023). "Interestingly, Bcl-2, an anti-apoptotic gene active in stem cells, is implicated in early tumor processes like budding, and its shifting expression during CRC progression underscores its contribution to tumor budding." (PMID 37760801, 2023). "Increased abundance of phenotypic meta-cluster 1, characterized by elevated CD45 and reduced BCL-2 expression, was significantly associated with a favorable treatment response and improved overall survival independent of tumor genetic abnormalities or patient demographic variables." (PMID 37217482, 2023). "This may include the upregulation of a proapoptotic protein, phorbol-12-myristate-13-acetate-induced protein 1 (NOXA), which may in turn interact with the anti-apoptotic proteins of the Bcl-2 subfamily, Bcl-XL and Bcl-2, resulting in the apoptotic death of the tumour cells." (PMID 36302993, 2023). "Mechanistically, IFN-γ directly acts on tumor cells to maintain survival (BCL2 and surviving expression) and stemness, decreases antigen presentation, enhances the expression of immunosuppressive molecules markedly ICBs and IDO, and leads to infiltration of tumor-associated neutrophil." (PMID 37275859, 2023). "Indeed, miR-15/16 are known tumor suppressors, best characterized in B cell leukemia, which affect cell growth by restricting cell-cycle and anti-apoptotic genes such as Ccnd1 (cyclin D1), Bmi1, Bcl2, and Mcl1." (PMID 37862171, 2023). "Even though Bcl-2 was referred to have a pro-tumourigenic role, consecutive studies reported that its function in different cell types was more sophisticated, and it may be involved in growth inhibition of tumour cells." (PMID 36939902, 2023). "Similarly, combining Bcl-2-targeted siRNA with anticancer drugs could promote the synergistic effect for tumor treatment." (PMID 36778126, 2023).